CD4 (CD4 molecule)
Diseases named in the same sentence as CD4 in open-access papers (continued):
Sharing a sentence is not in itself a finding about the gene and the disease.
cerebral malaria (17 papers, 2009 to 2022). A sequestration of Plasmodium falciparum in the brain, which can cause coma and/or seizures. "Here we show that Kcc1M935K/M935K mice are protected from the development of experimental cerebral malaria, and that this protection is associated with an increased CD4+ and TNFa response." (PMID 31015511, 2019). "We further show that cDC1 promote the differentiation of a type of parasite‐specific CD4 T cells that play a pathogenic role in cerebral malaria (Th1) and that they inhibit the development of regulatory IL‐10+ CD4 T cells." (PMID 28935714, 2017). "Given that recruitment of CD4+ and CD8+ T cells in the brain is a hallmark of cerebral malaria, a comparative analysis of CD4+ and CD8+ T cells infiltrating the brain was performed in H3R−/− and C57BL/6 mice." (PMID 19547708, 2009). "Cerebral malaria is associated with increased proportions of memory CD4+ T cells." (PMID 26581890, 2015). "Studies have found that in cerebral malaria, brain endothelial cells can present antigens and stimulate T cells to promote the activation of the effector CD4+ T cell response." (PMID 36591312, 2022). "There was a trend towards a more frequent expression of PD1 on CD4+ T cells in patients with severe cerebral malaria." (PMID 27802341, 2016). "A need for T cell priming in the pathogenesis of cerebral malaria is supported by increased memory to naive CD4+ lymphocytes compared with control children." (PMID 26581890, 2015). "Coculture of CD4+ T cells by IL-10+ B cells announced that IL-10+ B cells were in a position to induce CD4+T cells to produce large quantity of IL-10, which mediated the immunosuppression and protection from development of cerebral malaria." (PMID 24991577, 2014). "Furthermore mice depleted of CD4+CD25+ Tregs were resistant to experimental cerebral malaria." (PMID 31856836, 2019). "Thus, our study suggests that CTLA-4 may be much more effective than PD-1/PD-L1 at regulating CD4+ T cells particularly in this experimental model of cerebral malaria, although this hypothesis remains to be directly tested." (PMID 22319445, 2012). "Comparing the proportion of IFNγ+, IFNγ+ IL10+ and IL10+CD4+ T cells in patients with uncomplicated and severe cerebral malaria, we detected a trend towards a decreased proportion of IL10+CD4+ T cells in patients with severe cerebral malaria." (PMID 27802341, 2016). "CXCR3 expression was increased on spleen and brain CD4+ T cells in cerebral malaria mice compared to non-infected mice." (PMID 24498110, 2014). "While further work needs to be done to establish the role of CD4+ and CD8+ T cells in the brain of infected pups, as they are required for experimental cerebral malaria;42 both cell types also make IFNγ that is essential to experimental cerebral malaria in adult mice." (PMID 36131528, 2022). "Also γδ T, CD4+ T and, more pronounced, CD8+ T cells were significantly increased in the brain of mice that developed cerebral malaria compared to non-infected mice." (PMID 24498110, 2014). "The mechanisms by which CD4+ T cells mediate cerebral complications have not been fully elucidated, but it is thought to involve the production of Th1-type cytokines, such as IFN-γ, that exacerbate the inflammatory cascade responsible for local and systemic inflammation in cerebral malaria." (PMID 34025654, 2021).
common variable immunodeficiency (17 papers, 2010 to 2025). "Analysis of naive CD4+ T-cells remains to be determined since such phenotype has been associated with a high risk of infection in patients with common variable immunodeficiency." (PMID 31052269, 2019). "In adult patients that have been diagnosed with common-variable immunodeficiency (CVID), a condition mostly affecting B cells and antibody levels, the low proportion of naïve CD4 T cells is associated with more complications and a poor prognosis." (PMID 39946072, 2025). "CD4 T regulatory cells (CD4 Tregs) have been investigated in common variable immunodeficiency (CVID)." (PMID 35669770, 2022). "Immunological follow-up reveals a previously unidentified gradual depletion of B and CD4+ T cells in all three presented patients with transition of a common variable immunodeficiency (CVID)-like disease to late-onset-CID in one of them." (PMID 30987377, 2019). "On the contrary, patients with B cell disorders such as x-linked agammaglobulinemia and common variable immunodeficiency (CVID) are reported to rarely present with PCP, suggesting a B cell-independent CD4+ T cell priming mechanism." (PMID 31010170, 2019). "pRD can also present as chronic infections with Cytomegalovirus (CMV) or Epstein-Barr virus (EBV) accompanied by γδ T cell expansion, idiopathic CD4+ T cell lymphopenia (ICL), common variable immunodeficiency (CVID), and selective IgA deficiency (SIgAD)." (PMID 37475856, 2023). "Patients with common variable immunodeficiency disorder (CVID) share characteristics including hypogammaglobulinemia, impaired B cell function, cytopenia, a low frequency of naive CD4+ T cells, an increase in cellular activation, and a skewed distribution of circulating B cell subsets." (PMID 20844745, 2010).
disseminated tuberculosis (17 papers, 2009 to 2026). "In the adjusted analysis the associated factors with mortality were: CD4 ≤ 50 cells/mm3 (HR: 3.10; 95% CI: 1.720 to 5.580; p = 0.00); mechanical ventilation (HR: 2.81; 95% CI: 1.170 to 6.760; p = 0.02); and disseminated tuberculosis (HR: 3.70; 95% CI: 1.290 to 10.590, p = 0.01)." (PMID 28558689, 2017). "A 53-year-old Nepalese man who had been living in Japan was diagnosed with HIV infection (CD4 count, 146 cells/μL) and miliary tuberculosis." (PMID 41327427, 2025). "Consequently, the CAR, extrapulmonary disseminated tuberculosis, other pulmonary infectious diseases, pulmonary cavitation, and CD4+ T-cell counts were identified and used to establish a prognostic nomogram." (PMID 40510348, 2025). "Reliable diagnosis of CM is cheap and more accessible than other indicators of advanced HIV disease burden such as CD4 testing or investigation for disseminated tuberculosis; therefore, monitoring CM incidence has the potential to serve as a valuable metric of HIV programmatic success." (PMID 38330295, 2024). "In a sensitivity analysis, the hazard ratio for mortality was 1.44 (95% CI, 1.16–1.79, P = 0.001) after adjusting for age, serum albumin, CD4 cell counts, homelessness, illiteracy, belonging to a disadvantaged community, gender, positive sputum smear, disseminated tuberculosis, and previous ATT." (PMID 25013814, 2014). "Among seven cases of disseminated tuberculosis, five had comorbid HIV infection, with all patients having a cluster of differentiation 4 (CD4) count of less than 50 cells/μL." (PMID 33110716, 2020).
herpesvirus infections (17 papers, 2009 to 2025). "Patients with CD4 T cell deficiencies have an increased susceptibility to herpesvirus infections." (PMID 26599878, 2015). "CD4 T cell responses have been shown to be a major determinant in the control of herpesvirus infections in animal models and in humans." (PMID 26599878, 2015). "In animal models of herpesvirus infections, there is strong evidence for CD4 immune T cells affording anti-viral protection independently of their traditional helper activities." (PMID 23012630, 2012). "Here we review, with emphasis on human herpesvirus infections, the strategies evolved to evade CD4 T cell immunity." (PMID 23012630, 2012). "Interestingly, using a large immunophenotyping panel, the highest AUC was 0.69 [0.54–0.84] for CD4+/CD8+ ratio to discriminate patients with ongoing Herpesviridae infection." (PMID 40796210, 2025). "However, it is in herpesvirus infections that CD4 CTLs are perhaps best known, as they have been observed in response to all three families of human herpesviruses (52, –, 54)." (PMID 36445084, 2022). "In human recurrent herpes infections, both CD4+ and CD8+ TRM persisting between lesions may control asymptomatic shedding through interferon-gamma secretion, although this has been more clearly shown for CD8+ T cells." (PMID 33668777, 2021). "Histopathological and cytological examination was in favor of a herpes infection, the culture confirmed the herpes infection.The patient had a CD4 count of 159 elements/mm3, and a viral load of 71 copies/ml, negative syphilitic serology, negative CMV PCR and normal fundus." (PMID 32117522, 2020). "Below, we summarise the CD4 T cell responses to human herpesvirus infections." (PMID 23012630, 2012). "CD4 T cells responding to antigens presented on major histocompatibility complex class II (MHC-II) molecules are known to play an important role in controlling herpesvirus infections." (PMID 23012630, 2012). "The accumulation of past infections, including the number of herpesvirus infections, did not explain the baseline CD4+ T cell phenotype." (PMID 39938525, 2025).
intestinal inflammation (17 papers, 2005 to 2025). "Thirdly, over-expression of T-bet in CD4+ T cells could directly inhibit the expression of FoxP3, because Th1 polarization is reported to underlie the pathogenesis of intestinal inflammation 24–26." (PMID 25219397, 2015). "Patients with low CD4+ also had a higher prevalence of gastroenteritis (11/43, 25.6% vs 0/18, P = 0.0246)." (PMID 35257272, 2022). "Therefore, in this study, we investigated the immunoregulatory effects of DCs and iNKT cells on CD4+ T cell polarization in the MLNs during DSS-induced intestinal inflammation." (PMID 36499642, 2022). "Intestinal inflammation in piglets was induced by intraperitoneal injection of LPS for 4 h, including an increase in leukocytes and the percentage of monocytes, eosinophils, basophils and CD8+ T cells in the whole blood and a decrease in the ratio of CD4+/CD8+ T cells (p < 0.05)." (PMID 40129578, 2025).
liver failure (17 papers, 2012 to 2024). A liver disease characterized by the liver losing or has lost all of its function. "Of note, inhibitory features of CD4+CXCR5−FOXP3+ T cells were closely associated with poor outcomes (hepatic failure)." (PMID 36635631, 2023). "In conclusion, patients with PBC liver failure might have a relatively immunosuppressed state, predominantly caused by lymphocytopenia, which was probably related to the intervention of IL-2 on CD4 cell differentiation." (PMID 36159788, 2022). "Since liver failure can lead to a significant decrease in the percentage of CD4+ T cells, we detected a rather lower percentage of CD4+ T cells in LTR with the high MELD scores." (PMID 35047528, 2021). "Patients with immunosuppressive conditions including hypoproteinemia, post-chemotherapy, kidney transplantation, and hepatic failure had both significantly lower number and lower function of CD4+, CD8+ T cells, and NK cells than healthy controls." (PMID 31857499, 2019). "In this study, we used ConA to induce acute liver injury, in order to create a model in which to characterize CD4+ T-cell activation, subsequent inflammation, the types of cell death, and liver failure." (PMID 26089871, 2015). "In this study, we used ConA to induce acute liver injury to create a model of liver injury in which to characterize CD4+ T-cell activation, subsequent inflammation, the kinds of cell death, and possibly ultimate liver failure." (PMID 25120564, 2014). "Taken together, our results prove the upregulation of inhibitory markers of CD4+CXCR5−FOXP3+ T cells in chronic HBV infection and HBV-related liver failure, further suggesting that they may be associated with dysregulated anti-HBV immune response." (PMID 36635631, 2023). "To address the features of circulating CD4+CXCR5−FOXP3+ T cells in chronic HBV infection, we next compared HC subjects, treatment-naïve patients, and patients with HBV-related hepatic failure." (PMID 36635631, 2023). "The study revealed an upregulation of immunosuppressive features, such as CTLA-4 and PD-1, on CD4+CXCR5−FOXP3+ T cells in treatment-naïve CHB patients and in patients with HBV-related hepatic failure compared to healthy controls." (PMID 37243227, 2023). "Potential pharmacological targets for the treatment of liver failure include miR-126a, and miR-126a-5p has promising potential to be developed as a new drug because it downregulates DLK1 and promotes CD4 T-cell differentiation toward Th1." (PMID 36555554, 2022). "Patients with HBV-related ACLF exhibited an increase in circulating CD4+CD25+ Tregs, which was correlated with HBV-related liver failure." (PMID 22978653, 2012). "KCs may primarily secrete Gal-9 in liver tissues, and Gal-9 may play an immunomodulatory role in liver failure by engaging in immune regulation via CD8 + and CD4 + T cells." (PMID 39333198, 2024). "Although the frequency of CD4+CXCR5−FOXP3+ T cells in the HBV-infected patients was comparable with HC subjects, eAg−CHep patients showed notable reduced CD4+CXCR5−FOXP3+ T cell frequency in comparison to eAg+CInf, eAg−CInf, and hepatic failure patients." (PMID 36635631, 2023). "As we did not perform T-cell-marker-specific staining (as CD4 and CD8), and it is not a routine therapy option in checkpoint-inhibitor-transmitted hepatic failure, we did not consider this therapy option." (PMID 37510756, 2023).
migraine (17 papers, 2016 to 2025). "Among them, Alb, Tgfb1, Icam1, CD4, and Ptprc are explicitly or potentially implicated in immune-inflammatory and oxidative stress mechanisms involved in migraine pathophysiology." (PMID 40699640, 2025). "Compared with that in healthy subjects, a significant increase in CD4+ and a decrease in CD8+ populations has been found in migraine patients, which was associated with a reduction in immunoregulatory CD4+CD25+ cell levels." (PMID 33958992, 2021). "The present study aims to establish whether these three common SNVs in the LAG3 and CD4 genes are associated with the risk for migraine." (PMID 36674807, 2023). "In this study, we investigated the possible association between common variants in the LAG3/CD4 genes (both genes, which are closely related, encode proteins involved in inflammatory and autoimmune responses) in the risk of migraine in a cohort of Caucasian Spanish participants." (PMID 36674807, 2023). "In this study, we identified that NTG-induced migraine is associated with the PI3K–Akt signaling pathway, cytokines and their receptor interactions, and nine key hub genes (Alb, Tgfb1, Cd4, Ptprc, Itgb1, Icam1, Col1a1, Pxdn, and Itgad) through transcriptomics." (PMID 40699640, 2025). "Likely correlated with the upregulation of Madcam expression by CGRP, we also discovered a significant increase in the relative abundance of CD4+ T cells expressing LPAM1 (α4β7 integrin) in the DCLNs of mice with NTG-induced migraine." (PMID 38743922, 2024). "One study on 22 migraine patients found alterations in lymphocyte subsets (increase in CD4+, decrease in CD8+) in the peripheral blood of migraine patients outside the attacks, but this finding was not replicated in other studies." (PMID 38110925, 2023). "We detected a significantly lower peripheral blood CD4+ and its subgroup CD4+ CD25 + T cells in the migraine group compared to the matched healthy controls even after controlling for covariates." (PMID 35896985, 2022). "The CD18 MFI on CD4+ helper T cells in matched control and migraine group were 735 ± 139 and 619 ± 135, respectively (p = 0.06)." (PMID 35896985, 2022). "In the pathogenesis of migraine, research has discovered considerable changes in the levels of regulatory T cells (CD4+ and CD25+)." (PMID 36295508, 2022). "The finding of relatively lower CD4+ CD25+ T cells in migraineurs is consistent with a previous migraine study." (PMID 35896985, 2022). "In our migraine group, CD4+ T cells were significantly lower and CD8+ T cells were slightly higher in the migraine group compared with the control group." (PMID 35896985, 2022). "In 2006, Du and colleagues reported that the genes significantly up-regulated by migraine were mostly from platelet/monocytes, while others were from PMNs, CD4+, CD8+ T cells, and NK cells." (PMID 35896985, 2022). "Interestingly, a lower value of CD4+ TEM (effector memory helper T lymphocytes) appears to represent a potential biomarker determining the severity of migraine." (PMID 38397400, 2024). "For this purpose, the frequencies of CD4 rs1922452, CD4 rs951818, and LAG3 rs870849 genotypes and allelic variants, using a specific TaqMan-based qPCR assay, were assessed in 290 patients diagnosed with migraine and in 300 healthy controls." (PMID 36674807, 2023). "The HIT-6 migraine outcome was (much) better explained by CD4 + TEM (33%) than by age (15%)." (PMID 32704149, 2020). "Results of this study show that CD4 + TEM could be a biomarker that determines the severity of migraine." (PMID 32704149, 2020). "Besides, headaches are more frequent after the second vaccination of mRNA vaccines, CD4 + T-cell expresses with Th1 cytokines like TNF-α, which can sensitize meningeal nociceptors and stimulate the synthesis of the migraine-associated calcitonin gene-related peptide." (PMID 38431578, 2024).
migraine (continued). "Despite LAG3 and CD4 not having been the matter of study in migraine patients, the possible role of inflammatory factors in migraine, together with the important role of these proteins in the inflammatory and immune response, suggest that LAG3 and CD4 could be interesting as markers of migraine." (PMID 36674807, 2023). "The CD4 + TEM may represent a potential biomarker that determines the severity of migraine." (PMID 32704149, 2020). "In this study, transcriptomic analysis revealed significant downregulation of Alb and upregulation of Tgfb1, Icam1, CD4, and Ptprc in NTG-induced migraine model rats." (PMID 40699640, 2025). "CD4+CD25+ T cell percentages in matched control and migraine groups were about 8.3% and 5.7% of CD3+ T cells respectively (p = 0.001)." (PMID 35896985, 2022). "In our migraine group, CD4 + T cells were significantly lower(64 ± 5.45 vs. 70.6 ± 8.92) (p = 0.035) and CD8 + T cells were slightly higher (p = 0.3) in the migraine group compared with the control group." (PMID 35896985, 2022). "Moreover, some evidence supports long-lasting alterations in some of the pro-inflammatory cytokines (increased TNF-α, IL-1β, IL-6 and IL-8) and lymphocyte subsets (increase in CD4+, decrease in CD8+) in the peripheral blood of migraine patients." (PMID 38110925, 2023). "However, and taking into account this main limitation, this study suggests the absence of association between CD4 rs1922452, CD4 rs951818, and LAG3 rs870849 SNVs and the risk of developing migraine in the Spanish Caucasian population." (PMID 36674807, 2023). "Furthermore, the CD4+CD25+ population was significantly lower in migraine patients compared to healthy volunteers, suggesting that migraine may be related to autoimmunity." (PMID 35896985, 2022). "CD4+ Th cells produce IL-10, a primarily anti-inflammatory cytokine which also activates B cells, and plasma levels of IL-10 have been shown to be increased during migraine attacks in patients with migraine without aura, suggesting systematic inflammation in migraine pathogenesis." (PMID 39407099, 2024). "Interestingly, significant changes in the CD4+ effector memory T cells and terminally differentiated CD8+ T lymphocytes have been observed in migraine patients without aura, despite the interictal phase, with possible implications on disease severity." (PMID 37176011, 2023). "In the peripheral blood of a cohort of children and adolescents suffering from migraine without aura, migraine with aura, and hemiplegic migraine, CD8+ prevalence was lower, and the CD4+/CD8+ lymphocytes ratio was higher in the ictal phase irrespective of the subtype of migraine." (PMID 37176011, 2023). "CD4 + TEM may be a new biomarker, one that assesses the severity of migraine in patients without prophylactic treatment." (PMID 32704149, 2020).